PPARD (peroxisome proliferator activated receptor delta)
Diseases named in the same sentence as PPARD in open-access papers (continued):
Sharing a sentence is not in itself a finding about the gene and the disease.
Obesity (continued). "Here, our data showed that PPARδ is needed for BBR to exert an inhibitory effect on lipid accumulation to reduce obesity, which boosts our understating of the role of PPARδ in the effect of BBR and provides novel insight for developing BBR into an anti-obesity medication." (PMID 37511356, 2023). "Besides, the preventive and therapeutic effects of ginger in obesity are mediated via multiple mechanisms, such as increasing leptin and HDL-cholesterol levels, elevating skeletal muscle fat catabolism, and activation of AMPK and PPARδ pathways." (PMID 35949312, 2022). "The activation of RXR/PPARδ in muscle by CNX-013-B2 and increased mRNA expression of UCP3 could be one of the reasons for the protection from high fat-induced insulin resistance and obesity." (PMID 25143786, 2014). "Obesity- and diabetes-induced type I to type II fiber transition and decreases of oxidative capacity of skeletal muscle has been explained by down-regulation of peroxisome proliferator-activated receptor γ, coactivator-1α (PGC-1α) and peroxisome proliferator-activated receptor δ (PPARδ)." (PMID 23842456, 2013).
metabolic syndrome (102 papers, 2005 to 2025). A cluster of metabolic risk factors for CARDIOVASCULAR DISEASES and TYPE 2 DIABETES MELLITUS. "PPARδ therapies have complementary effects in improving lipoprotein subfractions associated with atherogenic dyslipidemia." (PMID 25849380, 2015). "Hitherto, the associations between PPARD +294C and dyslipidemia, CHD, and other age-related pathologies have been replicated in several populations." (PMID 25873088, 2015). "PPARδ can help normal cells endure metabolic challenges, and its agonists may be used to treat metabolic syndrome-associated abnormalities." (PMID 39292167, 2024). "Studies in Chinese Han population have shown that PPARD rs2016520 variant (also named +294T > C or -87T > C) is associated with blood glucose, insulin level and insulin resistance, and is a key factor affecting the development of metabolic syndrome and T2DM." (PMID 36051387, 2022). "The impact on the regulation of lipid and carbohydrate metabolism observed for PPARδ has led to the hypothesis that genetic variation within the human PPARδ gene may be associated with human disease such as the metabolic syndrome and/or coronary heart disease." (PMID 23431284, 2013). "Large-scale clinical studies in the Chinese population have shown that PPARD rs2016520 polymorphism (also named + 294 T > C or − 87 T > C) is associated with blood glucose, insulin level and insulin resistance, and is a key factor affecting the development of metabolic syndrome and T2DM." (PMID 34772419, 2021). "PPARδ-selective agonists, such as seladelpar, are expected to be effective against dyslipidemia, diabetes, obesity, liver diseases, and sporadic inclusion body myositis." (PMID 40298866, 2025). "Pan-NR agonists, such as RGX-202, activate PPARα, PPARγ, and PPARδ, leading to improvements in lipid metabolism, insulin sensitivity, and fatty acid oxidation, with potential applications for metabolic syndrome, dyslipidemia, and CVD." (PMID 40926269, 2025). "PPARδ agonists are currently under investigation for neuroprotection, muscle regeneration, and treating metabolic syndrome." (PMID 40926269, 2025). "PPARδ agonists have been used in the treatment of dyslipidemia and metabolic syndrome and are promising agents for the treatment of several metabolic disorders." (PMID 38279176, 2024). "Mechanistically, we uncovered that Smad3 targeted peroxisome proliferator-activated receptor delta (PPARδ) to induce dyslipidemia and NAFLD in db/db mice, which was improved by genetically deleting and pharmacologically inhibiting Smad3." (PMID 37511155, 2023). "We herein reveal five novel high-resolution structures of PPARδ/γ–bezafibrate, PPARγ–fenofibric acid, and PPARδ/γ–pemafibrate, thereby providing the molecular basis for their application beyond dyslipidemia treatment." (PMID 35563117, 2022). "PPARδ agonist seladelpar decreases liver enzyme levels, inflammation marker levels, insulin resistance, circulating, and atherogenic dyslipidemia." (PMID 34745420, 2021). "Use of hepatocyte-specific PPARδ null mice identified that hepatic PPARβ/δ augments FA muscle utilization and improves dyslipidemia through a metabolic network between hepatic PPARβ/δ and muscle PPARα." (PMID 34361064, 2021). "Collectively, PpardΔHEP mice identified a novel role of hepatic PPARβ/δ that enhances hepatic synthesis, muscle FA utilization, and improved dyslipidemia through a metabolic network between hepatic PPARδ–PC (18:0/18:1)–muscle PPARα." (PMID 32192216, 2020). "Our novel finding suggested that glomerular hypertrophy was associated with decreasing PPARδ expression and elevating phosphorylation of p38 MAPK in rats on HFD-induced metabolic syndrome." (PMID 31073415, 2019). "PPARδ is ubiquitously expressed and a target for management by the different components of metabolic syndrome." (PMID 30060458, 2018). "Activation of PPARδ stimulates fatty acid oxidation in adipose tissue and skeletal muscle and improves dyslipidemia in mice and humans." (PMID 28404991, 2017).
metabolic syndrome (continued). "In this study we investigated the role of intestinal PPARδ in energy metabolism and the development of metabolic syndrome using mice with an intestinal epithelial cell (IEC) specific deletion of PPARδ." (PMID 28404991, 2017). "In the present study we evaluated a possible role of PPARδ in the intestine in energy metabolism and the development of metabolic syndrome using mice with an intestinal epithelial specific deletion of the PPARδ gene." (PMID 28404991, 2017). "Taken together, our findings support intestinal-specific activation of PPARδ as a therapeutic approach for the treatment of dyslipidemia and other aspects of metabolic syndrome, while avoiding systemic toxicity." (PMID 28404991, 2017). "To determine the role of intestinal PPARδ in the development of metabolic syndrome we challenged PPARδIEC-KO mice and wild-type littermates for 10 wks with a HFD consisting of 60% kcal from fat." (PMID 28404991, 2017). "Synthetic PPARδ agonists have proven to be effective also in preclinical model of diabetes and dyslipidemia, and preliminary results are also available for steatosis." (PMID 23431284, 2013). "The present study demonstrated that rosiglitazone improved endothelial function in isolated arteries from a rat model of metabolic syndrome through both PPARγ- and PPARδ-mediated phosphorylation of Akt and eNOS." (PMID 22190906, 2011). "Activation of PPARδ has been shown to prevent dyslipidemia and obesity in animal models of metabolic syndromes." (PMID 19636418, 2009). "No PPARδ ligands are currently used as such in treatment of disease, although studies on human subjects for the use of a PPARδ agonist in the treatment of metabolic syndrome have been reported." (PMID 19756148, 2009). "Ongoing Phase II clinical trials of GW-501516, a PPARδ agonist for the potential treatment of dyslipidemia by GlaxoSmithKline and Ligand are soon to be released." (PMID 19696948, 2009). "PPARδ agonists produce complex actions as shown by their tumor promoting effects in rodents and their cholesterol-lowering action in dyslipidemias." (PMID 18566686, 2008). "PPARδ activation improved both dyslipidemia and insulin sensitivity in rodent models, and PPARδ may be different or similar to PPARα/γ." (PMID 40298866, 2025). "Intriguingly, and of relevance to this work, the addition of PPARα agonistic activity to PPARγ, PPARγ, to PPARδ agonists has led to a higher safety profile, leading to their development for use in many diseases, including type 2 diabetes, dyslipidemia, and non-alcoholic fatty liver disease." (PMID 35288651, 2022). "Moreover, it has been shown that rosiglitazone restores endothelial dysfunction in a rat model of metabolic syndrome, through PPARγ- and PPARδ-dependent phosphorylation of eNOS and AKT." (PMID 31993046, 2019). "We and others have previously demonstrated that synthetic PPARδ agonists such as GW501516 and GW0742 could ameliorate a number of pathological features associated with diabetes and metabolic syndrome." (PMID 28067284, 2017). "PPARD has been shown to be involved in regulation of lipid and glucose metabolism and related disorders, and is considered a promising drug target for the treatment of metabolic syndrome diseases." (PMID 24391853, 2013). "Further, comprehensive analysis of the PPARD gene could be helpful in drug design, since PPARD provides an attractive target for therapeutic intervention so far in patients with metabolic syndrome." (PMID 24391853, 2013). "PPARδ agonists are currently in Phase II clinical trials for dyslipidemia." (PMID 19789638, 2010). "Although the physiological ligands of PPARδ remain undefined, a number of high affinity synthetic ligands have been developed for the receptor as a therapeutic target for type 2 diabetes mellitus, dyslipidemia and the metabolic syndrome." (PMID 19968882, 2009). "All these observations suggest that PPARδ may bean effective target for the treatment of metabolic syndrome." (PMID 18566690, 2008).
metabolic syndrome (continued). "The results of these studiessuggest that sooner or later high-affinity PPARδ synthetic drugs which uniquelytarget multiple components of the metabolic syndrome, including obesity,insulin resistance, hyperglycemia, dyslipidemia, and atherosclerosis will enterthe market." (PMID 18645617, 2008). "However, in the case of PPARδ, the authors suggest that it may also be an important therapeutic target for selected patients’ disorders, including cancer, infertility, and dyslipidemia." (PMID 39062500, 2024). "Similarly liver-specific PPARδ KO presented with insulin resistance, dyslipidemia, and steatosis." (PMID 37173315, 2023). "Notably, PPARδ agonists are developed for the improved treatment of metabolic syndrome." (PMID 32041341, 2020). "Interestingly, mutations in the PPARD gene are associated with BD in the American population; thus there might be also a direct deficit of PPARD in patients with BD leading to the development of metabolic syndrome." (PMID 24799886, 2014). "Agonists of peroxisome proliferator-activated receptors (PPARα, PPARγ, PPARδ) regulate lipoprotein metabolism, fatty acid oxidation, glucose homeostasis and inflammation, and therefore are used as anti-diabetic drugs for treatment of dyslipidemia and insulin insistence." (PMID 19636418, 2009). "Together, our findings show that intestinal PPARδ is important in maintaining metabolic homeostasis and suggest that intestinal-specific activation of PPARδ could be a therapeutic approach for treatment of the metabolic syndrome and dyslipidemia, while avoiding systemic toxicity." (PMID 28404991, 2017). "Consequently, the therapeutic regulation of PPARδ activity using selective agonists has been proposed for many varied disorders including: lung cancer, experimental autoimmune encephalomyelitis, skin disorders such as psoriasis and cancer, type 2 diabetes, metabolic syndrome and dyslipidemias." (PMID 16672050, 2006). "Cardarine (C21H18F3NO3S2), better known by the popular name of GW501516, is a peroxisome proliferator-activated receptor delta (PPR-δ) agonist that presents potential use in the approach of cardiovascular diseases and metabolic disorders, dyslipidemia, and insulin resistance." (PMID 40006519, 2025). "The fine-tune regulation of NR4A receptors in monocytic lineage cells and their relevant role in metabolism, have led to propose NOR-1, together with PPARδ, another NR which modulates macrophage function and inflammation, as biomarkers of metabolic syndrome." (PMID 34768801, 2021). "PPARδ is the least well-defined subtype among the PPARs, but recentbiological study has disclosed that its activation significantlyincreases HDL cholesterol levels, and it influences glycemic control in aprimate model of metabolic syndrome." (PMID 18566690, 2008). "Indeed, Random Forest Analysis determined that the expression of both NOR-1 and PPARδ were specifically decreased in CD14+ cells (mainly monocytes) from patients with metabolic syndrome, identifying these patients with high specificity and sensitivity." (PMID 34768801, 2021). "Elafibranor and GFT505, which act as dual PPARα and PPARδ agonists, have shown a good response in the treatment of non-alcoholic steatohepatitis/non-alcoholic fatty liver disease (NASH/NAFLD) and its associated metabolic syndrome (MetS)." (PMID 34639224, 2021).
Insulin resistance (97 papers, 2004 to 2026). Increased resistance towards insulin, that is, diminished effectiveness of insulin in reducing blood glucose levels. "Common SNPs in PPARD are associated with an increased risk of impaired glucose tolerance, fasting glucose elevation and insulin resistance in populations with diverse ethnic backgrounds including Chinese, Korean and Mexican." (PMID 36051387, 2022). "To fully illustrate the role of PPARD on exenatide efficacy and its associated pathways in IR, we established the insulin resistance model in HepG2 cells." (PMID 36051387, 2022). "Microbiota analysis of subjects with PPARGC1A (rs 8192678) and PPARD (rs 2267668) SNPs revealed certain taxa associated with the development of insulin resistance and T2DM." (PMID 35205333, 2022). "Insulin resistance is linked to the neuroinflammation seen in AD, and it downregulates PPARD, a hormone receptor essential to the development of AD." (PMID 33920138, 2021). "In fact, specific ablation of M1-like macrophages restores insulin sensitivity and liver lipid levels in diet-induced obese mice, while deleting Pparδ, which promotes M2 polarization, thereby predisposing lean mice to develop insulin resistance." (PMID 29599925, 2018). "Simultaneous activation of PPARα, PPARδ and PPARγ by a single compound is being pursued to treat the multiple defects associated with insulin resistance, type 2 diabetes and the metabolic syndrome." (PMID 25143786, 2014). "The known involvement of PPARδ in insulin resistance, either directly or indirectly suggests that PPARD gene variants may account for individual differences in the clinical efficacy of exenatide." (PMID 36051387, 2022). "PPARD encoding PPAR-δ, which is related to islet function and insulin resistance, might directly or indirectly participate in the pathogenesis of T2DM." (PMID 34772419, 2021). "Another study also showed that PPARD polymorphisms (rs1053049, rs6902123 and rs2267668) could be involved in the development of insulin resistance and DM2." (PMID 29762540, 2018). "Regarding insulin resistance, intraperitoneal﻿ administration of ﻿PPARD agonist L-160, 043 to alcohol-exposed rats significantly increases the binding of insulin to IGF 1 and 2 receptors." (PMID 39899669, 2025). "Known effects of PPARD agonism on hepatocytes include increasing fatty acid oxidation, regulating energy metabolism, and ameliorating insulin resistance." (PMID 41180305, 2025). "Metrnl ameliorated lipid-induced inflammation and insulin resistance through AMPK- or peroxisome proliferator-activated receptor δ (PPARδ)-dependent signaling in mouse skeletal muscle." (PMID 40956671, 2025). "Regarding insulin resistance, activation of PPARD has been reported to improve high-fat diet-induced insulin resistance via the IL-6/signal transducer and activator of transcription 3 pathway by increasing AMP-activated protein kinase activity in mice." (PMID 39899669, 2025). "In an insulin resistant HepG2 cell model, the PPARδ agonists enhanced exenatide efficacy on insulin resistance, with the expression of GLP-1R being up-regulated markedly." (PMID 36051387, 2022). "To clarify the effect of insulin resistance on the expression level of PPARδ, we used RT-PCR and Western blot to detect the expression level of PPARδ in the liver tissues of db/db mice and in an insulin-resistant HepG2 cell model." (PMID 36051387, 2022). "PPARδ is engaged in glucose and lipid metabolism in the liver and exerts insulin-sensitizing effects, thereby improving hepatic insulin resistance." (PMID 36051387, 2022). "PPARδ activation reduces insulin resistance by regulating mitochondrial oxidation capacity in skeletal muscle, and the glucose-insulin cycle, thus enhancing glucose utilization and reducing triacylglycerol deposition." (PMID 35957821, 2022).